INS (insulin)
Diseases named in the same sentence as INS in open-access papers (continued):
Sharing a sentence is not in itself a finding about the gene and the disease.
diabetes (continued). "The importance of MafA for glucose homeostasis was shown in MafA-deficient mice, which displayed glucose intolerance after weaning due to impaired glucose-stimulated insulin secretion (GSIS) and age-dependent diabetes progression." (PMID 35454124, 2022). "Diabetes mellitus type 2 (DMT2) is a disease characterized by tissue resistance to insulin, hyperglycemia and decreased secretion of insulin by pancreatic β-cells." (PMID 36008981, 2022). "Li and coworkers synthesized enzyme-responsive micelles composed of poly(ethylene glycol)-b-poly(2-diisopropylaminoethyl methacrylate) (PEG-b-PDPA) block copolymers to study the insulin release behavior under glucose alterations for the treatment of diabetes mellitus (DM)." (PMID 35215689, 2022). "Type 2 diabetes mellitus (T2DM) is characterized by insufficient insulin secretion, an uncontrolled rise in blood glucose levels, and insulin resistance of peripheral tissues." (PMID 35821802, 2022). "Among patients with diabetes who were insulin-naive at the baseline, 36 (14%) patients in the ACEI or ARB group, and 9 (7%) in the ARNI group were initiated on insulin therapy (HR, 0.52; 95% CI 0.23–1.12; p = 0.094)." (PMID 35690600, 2022). "In type 1 diabetes mellitus (T1DM, previously known as insulin-dependent diabetes or juvenile diabetes) the pancreas is unable to produce any insulin." (PMID 35475576, 2022). "In vivo, when diabetes was induced in rats, the injection of PRP led to an increase in the number of β-cells, increased insulin secretion, improved blood-glucose control, and reduced oxidative stress." (PMID 35740440, 2022). "Although the uptake of insulin pumps and CGM is high among children in countries where access to diabetes technology is facilitated, the uptake of AID in children is protracted owing to the license status of commercially available AID systems." (PMID 35834298, 2022). "To assess the impacts of anti-diabetes agents, we excluded T2DM subjects who were treated with insulin sensitizers, insulin secretagogues, or insulin." (PMID 36331940, 2022). "Significant down-regulation (15% to 74%) of gene expression in diabetes biomarkers and decreases i n serum levels of fasting-glucose, HbA1c, hs-CRP, fasting-insulin, HOMA-IR, MDA (9% to 23%) were observed with NS-3 treated T2DM." (PMID 36540866, 2022). "More than 90% of diabetes cases are type 2 diabetes mellitus (T2DM), a metabolic disorder characterized by chronic hyperglycemia due to insufficient production of insulin by the pancreas or by insulin resistance." (PMID 35807309, 2022). "In experiments conducted on mice with experimentally induced MLD-STZ type 1 and type 2 diabetes, neratinib improved glycemia, insulin secretion, and β cell survival in a mouse model of MLD-STZ diabetes (type 1)." (PMID 35054822, 2022). "Previous studies showed that HIE is reduced in those with pre‐diabetes, and HIE is highly correlated with insulin sensitivity." (PMID 36411989, 2022). "However, some covariables like the duration of diabetes, insulin dose before transplantation, waiting time, and other factors reflecting diabetes-related comorbidities of recipients and donor factors which might be significantly different were not reported and adjusted." (PMID 34279713, 2022). "In this section, we will make a sketch of insulin signaling, TOR signaling, and AKH signaling in the fruit fly, which directly relates to diabetes in both insects and humans." (PMID 36035393, 2022). "Diabetes mellitus (DM)is a chronic complex disease, typicallyassociated with a state of hyperglycemia which occurs as a resultof scarce tissue responsiveness to insulin signaling (a conditionknown as insulin resistance) or insufficient secretion of the hormoneby pancreatic β-cells." (PMID 35924548, 2022).
diabetes (continued). "Thus, from both SAP and HCL populations, the diabetes-device dataset includes blood glucose data, recorded every ≈ 5 min from CGMs, as well as amounts and timestamps of bolus insulin doses, basal insulin doses, and carbohydrate amount entries from the insulin pumps." (PMID 35941355, 2022). "Regarding diabetes, the WHO notes that around 95 % of people with diabetes have ineffective use of insulin by the body, this type of diabetes is known as type 2 diabetes." (PMID 36090816, 2022). "The glucose AUC of the COS group was substantially lower (p < 0.05) than the diabetes model group, suggesting that COS enhanced the insulin sensitivity of T2DM mice." (PMID 38647883, 2022). "The two-way relationship between diabetes and periodontitis was mainly manifested in that untreated periodontitis could stimulate the production of antibodies by bacteria, induce the production of proinflammatory cytokines and then act on immune cells, thus promoting insulin resistance." (PMID 36131931, 2022). "High CGM accuracy is crucial for good diabetes management, especially when CGM readings are used for insulin dosing both alone or in combination with open/closed-loop systems." (PMID 35200366, 2022). "The two groups were matched according to sex, duration of diabetes mellitus, and in the case of patients with T2DM, only those who had insulin, or insulin and oral antidiabetics, for DM treatment were included so that the groups were in effect homogeneous." (PMID 36233694, 2022). "on 56 predominantly well-managed patients with diabetes (mean HbA1c 7.2%, 50/56 had T2DM) with minimal insulin/sulfonylurea use and 7 healthy controls." (PMID 35813638, 2022). "Besides, reducing injection frequency and adding short-acting insulin when the postprandial blood glucose is not satisfied after the use of long-acting insulin should be considered in older patients who need insulin to achieve satisfactory blood glucose control." (PMID 36249753, 2022). "Two different methods (modified International Diabetes Federation (IDF) criteria and IDF criteria along with insulin resistance) were applied to classify participants as metabolically healthy obese (MHO) or metabolically unhealthy obese (MUO)." (PMID 36038871, 2022). "While zooming in on different categories of CMD parameters, we found shared associations of BCAAs for all five glycemic traits, including fasting plasma levels of glucose, insulin, HbA1c, HOMA-IR index, and diabetes status." (PMID 36522747, 2022). "Here, we used two murine strains: prediabetic VH125.NOD and diabetes-resistant VH125.C57BL/6-H2g7 to explore the contribution of B cell affinity to a pancreatic islet antigen, insulin, in disease." (PMID 36275764, 2022). "Diabetes Mellitus (DM) is a metabolic disease caused by the lack of insulin synthesis, increased breakdown, or impaired insulin action." (PMID 36552346, 2022). "Moreover, according to another study, administering a short course of purified human AAT into NOD mice with new-onset diabetes, and which were treated with insulin, resulted in marked restoration of pancreatic β-cell mass and euglycemia, compared with mice that were treated with insulin alone." (PMID 35053215, 2022). "Ex vivo investigation of pancreatic islets in a model of diabetes and diet-induced obesity exhibited CGRP’s ability to block glucose-stimulated insulin secretion, insulin-2 gene expression and reduce glycolytic capacity." (PMID 36175833, 2022). "The prominent pathological feature of diabetes is insufficient insulin secretion (type 1 diabetes mellitus, T1DM) or unresponsiveness of peripheral tissues to insulin (type 2 diabetes mellitus, T2DM)." (PMID 35159300, 2022). "Adding log RBP4 to a basic riskmodel including age, BMI, diabetes duration, LVEF, insulin treatment, TG, LDL-C,eGFR, CRP, log NT-proBNP, retinopathy, nephropathy and neuropathy improved thec-index from 0.91 to 0.94 (p = 0.024)." (PMID 39076230, 2022).
diabetes (continued). "In this retrospective study, 33 patients with type 1 diabetes mellitus, regularly treated with multiple daily injection (MDI) insulin therapy, switched from their usual diet (high-carb, low fat) to an EVLCD (high fat, low carb)." (PMID 35956384, 2022). "Our present study aimed to reveal the correlation of beta-cell function and insulin sensitivity with glycemic control and weight control before and after MNT in patients with newly-diagnosed type 2 diabetes mellitus who started their treatment with MNT." (PMID 35658859, 2022). "The Diabetes Control and Complications Trial (DCCT) showed that intensive glycemic control improved the outcomes in patients with T1DM, and insulin therapy is the cornerstone." (PMID 35783304, 2022). "Type 1 diabetes mellitus (T1DM) is an autoimmune disease in which the body attacks the beta cells of the pancreas, which produce insulin." (PMID 35745165, 2022). "Effective treatment for T1D was concretely established in the cohort of the Diabetes Control and Complications Trial (DCCT; 1–3), which evidenced the necessity of intensive insulin therapy for the prevention of chronic complications of the disease." (PMID 36219199, 2022). "A study from the Better Diabetes Diagnosis cohort revealed that ~11% of patients with T1D had markedly elevated plasma IAPP levels relative to C-peptide and pro-insulin levels." (PMID 36359215, 2022). "Patients in moderate or high/very high risk group were mainly older, male, obese, had a longer duration of diabetes, higher baseline BMI, SBP, DBP, HbA1c, LDL-C and TG level, higher proportion of patients treated with insulin and ACEI/ARB." (PMID 35757423, 2022). "In this context, several clinical studies show the beneficial effect of fiber-enriched diets on health and in patients with pre-diabetes or T2DM, mainly in terms of increased insulin sensitivity, reduced fasting, and postprandial glucose." (PMID 35163038, 2022). "Diabetes mellitus (DM) is a chronic metabolic disease or disorder characterized by high blood sugar levels as well as impaired carbohydrate, lipid, and protein metabolism due to insulin function insufficiency." (PMID 36465856, 2022). "Since their advent in daily clinical practice, continuous subcutaneous insulin infusion (CSII) systems have been increasingly improved, leading to a high percentage of both adult and pediatric patients with diabetes now using insulin pumps." (PMID 36011925, 2022). "In one hand, α-synuclein is thought to inhibit insulin secretion by binding to KATP channels, resulting in insulin reduction, aggravating the process of diabetes." (PMID 36153375, 2022). "Type-I diabetes mellitus is characterized by complete lack of secretion of insulin, while Type II diabetes mellitus (DM) caused by the resistance of peripheral tissues to the action of insulin and inadequate compensatory secretion of insulin." (PMID 35388310, 2022). "This form of diabetes is commonly misdiagnosed as T1DM or T2DM and is often inappropriately managed with insulin, whereas the adequate treatment consists of a sulfonylurea." (PMID 35743358, 2022). "Diabetes mellitus (DM) is a disease associated with abnormally high levels of blood sugar (blood glucose) due to lack of insulin (type 1 diabetes—T1D) or insulin resistance (type 2 diabetes—T2D)." (PMID 36099285, 2022). "Carboxy peptidase E (Cpe), an enzyme that converts the pro-insulin to insulin, which suggest that Cpe may be related to the occurrence of T2DM, rescuing proinsulinmia caused by reduced CPE may be a new approach to treat early diabetes (Jo, Lockridge & Alejandro, 2019)." (PMID 36157062, 2022). "Additionally, a systematic review and meta-analysis showed that exogenous hyperinsulinemia increases the risk of dementia in diabetes patients compared to non-diabetes subjects and diabetes individuals not receiving insulin infusion, with RR of 1.83 and 1.36, respectively." (PMID 35682821, 2022).
diabetes (continued). "On a 6-year follow-up, according to laboratory findings and glucose measurements, diabetes progressed to T1DM and basal bolus insulin treatment (multidose insulin, MDI) with detemir and lispro was initiated." (PMID 35918735, 2022). "Type 2 diabetes mellitus (T2DM) is a progressive multi-system disease with variable degrees of deteriorating beta-cell function and insulin resistance, resulting in increased blood glucose levels and leading to premature death." (PMID 36483894, 2022). "Type 2 diabetes mellitus (T2DM) is a progressive metabolic disorder characterized by hyperglycemia resulting from the combination of resistance to insulin action, inadequate insulin secretion, and excessive or inappropriate glucagon secretion." (PMID 35409287, 2022). "Surprisingly, some patients in our study received other diabetes drugs (namely metformin, DPP4 inhibitors, SGLT2 inhibitors, and GLP1 receptor analogs) besides their insulin regimen." (PMID 35101023, 2022). "Interestingly, ONECUT1, a genetic risk gene for monogenic recessive diabetes, has been shown to directly repress expression of MAFA, the key regulator of insulin expression in β‐cells, suggesting that the regulatory network that underlies insulin control in vivo is maintained on‐chip." (PMID 36285680, 2022). "However, in both cases (SAP and HCL), a person with diabetes is expected to “announce meals" by entering the estimated carbohydrate amount into their insulin pump to determine and administer bolus insulin (i.e., larger amounts of fast-acting insulin) needed to account for food consumption." (PMID 35941355, 2022). "In our present study, serum ADA levels were observed to be positively correlated with ageing, higher SBP, longer diabetes duration, and increased levels of ALT, AST, GGT, CysC and HbA1c and negatively correlated with eGFR and insulin sensitivity index (IS-CP)." (PMID 36267565, 2022). "Type 2 diabetes mellitus (T2DM) is a chronic metabolic disorder characterized by persistent hyperglycemia due to impaired insulin secretion, peripheral tissue resistance to insulin action, or a combination of both." (PMID 36613109, 2022). "Induction of diabetes resulted in a significant (p < 0.05) increase in plasma GLUC, liver GLUC, INS, DPP-IV, AMY and TRIG by 153.5, 296.0, 152.0, 47.0, 610.0 and 83.2%, respectively, in diabetic rats compared with normal rats." (PMID 35739183, 2022). "Diabetes mellitus (DM) is a chronic metabolic disorder caused by a deficiency in insulin production or a lack of capability of the cells to use it properly." (PMID 35392258, 2022). "These associations were revealed after adjusting for age, sex, BMI, waist circumference, smoking habit, hypertension, family history of premature CVD, diabetes, HDL-C, LDL-C, insulin therapy, and statin therapy." (PMID 35659558, 2022). "Although the duration of diabetes and HbA1c levels were similar across the quartiles of UPCR, patients with higher levels of proteinuria were more likely to receive a prescription of insulin at the start of dialysis." (PMID 35213636, 2022). "Aromadendrin-3-O-rutinoside improved insulin resistance via PI3K- and AMPK-dependent pathways, thus being a potential candidate for the management of type 2 diabetes mellitus." (PMID 35684361, 2022). "The participants in this study are experienced in managing their diabetes while exercising, and in all cases the ICII was larger than the reported carbohydrate-insulin ratio, a relative reduction in insulin dose for the exercise period, as is recommended." (PMID 36992757, 2022). "Regarding diabetes treatment, subjects in the SH group versus those in the NSH group received lower doses of prandial insulin and higher doses of basal insulin." (PMID 36191264, 2022). "Diabetes Self-Management Education and Support (DSMES) is a strategy that can be used to empower and support insulin-treated individuals with T2D." (PMID 36197724, 2022).
diabetes (continued). "Additionally, insulin would be responsible for stimulating iron uptake by the cell, which could lead to an even greater accumulation of cellular iron, forming vicious cycle that could induce insulin resistance and diabetes mellitus." (PMID 36067799, 2022). "Over the past decade, there have been several advances in diabetes technology such as continuous glucose monitoring (CGM) systems, insulin delivery devices, and hybrid closed-loop systems." (PMID 35157505, 2022). "Type 2 diabetes mellitus (T2DM), a chronic metabolic disorder characterized by decreased insulin secretion and insulin resistance, is becoming a major health issue worldwide." (PMID 37430932, 2022). "Diabetes mellitus (DM) is a metabolic disorder of multiple etiologies characterized by chronic hyperglycemia with disturbances in carbohydrate, fat, and protein metabolism resulting from defects in insulin secretion, insulin action, or both." (PMID 35606785, 2022). "Low levels of glycine are related to diabetes and could potentially predict future T2D; they may also reflect glycine utilization towards glutathione production to counteract oxidative stress; and/or an increased uptake of glycine by insulin-resistant tissues to support gluconeogenesis." (PMID 35203426, 2022). "Type 2 diabetes mellitus (T2DM) is a chronic metabolic disease with high blood sugar in the context of insulin resistance and impaired insulin secretion." (PMID 36037202, 2022). "In comparison with insulin users and those with increasing HbA1c, the incidence of PDAC in diabetes patients initiating combination oral hypoglycemic treatment or those who did not meet any of the progression criteria was lower." (PMID 34728468, 2022). "Type-2 diabetes mellitus (T2DM) is a global epidemic attributed to the dysregulation of carbohydrate, lipid, and protein metabolism resulting from impaired insulin secretion, insulin resistance, or a combination of both." (PMID 35207564, 2022). "Diabetes mellitus (DM) is a metabolic disease characterized by hyperglycemia with impaired metabolism of carbohydrates, fats, and proteins because of insulin resistance and/or defects in insulin secretion." (PMID 35204091, 2022). "Type-1 Diabetes Mellitus (T1DM) is one of the most common endocrine and metabolic diseases in childhood in which insulin therapy is considered as a life-saving and life-long solution." (PMID 36221091, 2022). "Clinical trials in diabetes patients with omega-3 PUFAs, especially DHA and EPA, have reported that hypoglycemic and antidiabetic effects of omega-3 PUFAs are derived from insulin-sensitizing actions of DHA and EPA via SREBP, PPAR, and GLP-1 production." (PMID 36008962, 2022). "With an increasing duration of diabetes, the individual may be expecting this increase in glucose concentration with the athletic competition and take preventative measures to avoid race-day hyperglycemia such as injecting more insulin with any carbohydrates consumed pre-race." (PMID 36992757, 2022). "In patients with type 2 diabetes mellitus, GLP-1 promotes a significant increase in insulin sensitivity in both skeletal muscle and adipose tissue, with improvements in insulin-mediated glucose uptake." (PMID 35629915, 2022). "Of note, studies have shown that KLF14 can significantly regulate the metabolism of glucose and lipids in cases of type 2 diabetes mellitus (T2DM) and reduced insulin sensitivity." (PMID 34983946, 2022). "The tight relationship between mitochondrial dysfunction, reduced glucose-stimulated insulin secretion (GSIS), and diabetes development in human patients is acknowledged." (PMID 35626654, 2022). "Factors that can link diabetes and thyroid cancer risk could include, but are not limited to, elevated circulating level of insulin, increased body fat, hyperglycemia, and exogenous insulin use." (PMID 35158824, 2022).